MIR4309 (microRNA 4309)
Synonyms: hsa-mir-4309
Gene: MicroRNA gene on chromosome 14 (102,539,644 to 102,539,726, forward strand). Ensembl gene ENSG00000266015.
Diseases named in the same sentence as MIR4309 in open-access papers:
MIR4309 is named in the same sentence as 2 diseases in open-access papers, as found by Europe PMC text mining. Sharing a sentence is not in itself a finding about the gene and the disease. The quoted sentences say what the papers report.
depression (1 paper, 2023). "MIR4309 has been found to be significantly elevated among patients with disordered sleep (a core symptom of depression), as well as up-regulated in tissues of gastric cancer." (PMID 37143087, 2023). "While its direct involvement in the development of depression or BC is not known, this SNP interacts with several genes that have already been reported (i.e., TRAF3 and RCOR1), or that could play a role in the pathogenesis of the two traits (i.e., AMN, ANKRD9, and MIR4309)." (PMID 37143087, 2023).
MIR4309 also shares sentences with these, for which no sentence is quoted: gastric cancer (1 paper).